IL25 (interleukin 25)
Diseases named in the same sentence as IL25 in open-access papers (continued):
Sharing a sentence is not in itself a finding about the gene and the disease.
tumor (72 papers, 2012 to 2025). "For example, in a genetic mouse model of Apc mutation‐driven CRC, high IL‐25 expression (by tuft cells) and IL‐25R‐expressing tumour‐resident ILC2s are associated with impaired anti‐tumour responses and reduced survival." (PMID 40899118, 2025). "Several studies have shown that inflammatory cytokines, including IL-1, IL-6, TNF-α, and IL-25, are crucial in increasing tumor-associated inflammation, metastasis, angiogenesis, and apoptotic induction." (PMID 39267848, 2024). "As we have shown in human CRC patients, high tumor IL25 expression is associated with poor CRC patient survival, whereas IL33 expression does not discriminate between better or worse prognosis." (PMID 35658010, 2022). "IL-25 promotes tumorigenesis through maintaining tumour stemness, and genetic IL-25-deficiency led to reduced expression of stem cell markers Lgr5, CD133 and DCLK1." (PMID 36263033, 2022). "Genetic deficiency of IL-25 reduced CAC tumour burden and prolonged survival in one study, however others reported that antibody-mediated blockade of IL-25 instead enhanced CAC." (PMID 36263033, 2022). "Given the potential association of M-MDSCs with the IL-25-mediated tumor microenvironment, we additionally enriched for tumor M-MDSCs for scRNAseq." (PMID 35658010, 2022). "Recently, analysis of the publicly available gene expression databases found that high IL25 expression by CRC tumours was associated with reduced CRC patient disease-free survival." (PMID 36263033, 2022). "Using a mouse model of APC-mutation-driven CRC, IL-25-activated intratumoral ILC2s promoted intestinal tumorigenesis through enhancing M-MDSC-mediated suppression of anti-tumor immunity." (PMID 35658010, 2022). "Ablation of IL-25 signaling reduced tumour load, ILC2s and extended survival of IL-25-deficient Apc1322T/+ mice." (PMID 36263033, 2022). "Since IL‐25 has been dysregulated in tumor tissues and this dysregulation is involved in cancer development, its examination can be used as a tumor diagnostic and prognostic biomarker." (PMID 34128588, 2021). "It is noted that tumor-associated epithelial cells expressed higher levels of IL-25 compared with the para-tumor areas as shown by the positive areas." (PMID 27909985, 2017). "Consistent with the immunofluorescence results, IL-25 expression in tumor-associated CD4+ cells and macrophages was >50 folds higher than in CD45- cells." (PMID 27909985, 2017). "It was assumed that if the gene encoding for IL-25 be transferred into the MSCs then these cells will release the IL-25 within the tumor environment." (PMID 29326689, 2017). "IL-25 has also been implicated in tumor progression and was shown to inhibit the growth of various transplanted tumors in nude mouse models, and normal mammary epithelial-cell derived IL-25 exhibited cytotoxic activity in tumor cells." (PMID 26840565, 2016). "Here, the authors show that a synthetic phytochemical can be used to induce the secretion of Interleukin-25 from tumour associated fibroblasts resulting in impaired tumour metastasis." (PMID 27089063, 2016). "Future identification of specific cellular target(s) for Q2-3 is critical for realizing the stimulatory mechanism of Q2-3-induced IL-25 expression by fibroblasts or normal epithelial cells present in the tumour-associated lung microenvironment." (PMID 27089063, 2016). "Through our integrated clinical-biomarker–immunologic analyses derived from a diverse, pan-tumor cohort, we found that early increases in Th17 (IL-6, IL-17f), type 2 (IL-5, IL-13, IL-25), and type 1 (TNF-α) cytokines were associated with the development of grade ≥ 2 irAEs." (PMID 39403935, 2024). "In human CRC patients, increased tumour IL-25 expression is associated with poor prognosis, indicating that blocking IL-25 signalling may be a potential novel therapeutic option." (PMID 37455828, 2023). "Genetic IL-25 deficiency led to a reduction in tumour Mmp9 expression in AOM/DSS mice, indicating that IL-25 may induce MMP9 expression in CRC." (PMID 36263033, 2022).
tumor (continued). "Whether it is the acquisition of DCLK1+ expression by tumour stem cells due to aberrant Wnt signaling (for example due to loss of APC) which leads to their ability to produce IL-25 remains to be explored." (PMID 36263033, 2022). "In addition, IL-25 values are associated with several pathological features that represent tumor aggressiveness and/or poor prognosis." (PMID 36119529, 2022). "Interestingly, genetic IL-25-deficiency also led to a reduction in tumour Mmp2 in AOM/DSS-mediated CAC." (PMID 36263033, 2022). "The density of IL-25+ cells in GC tumor tissues was associated with histological grade and could serve as a predictor of favorable prognosis in patients with GC." (PMID 26840565, 2016). "However, there were several tumor-associated gene expression levels that were significantly reduced in the IL-25−/− (and some IL-25+/−) mice." (PMID 27165713, 2016). "The study suggested IL-25 might be secreted from tumor-associated fibroblasts (TAFs)." (PMID 37005677, 2023). "Notably, racemate of this dihydrobenzofuran lignan was recently reported as a highly promising antimetastatic agent that exerts this activity in vivo through its interaction with the tumor microenvironment by inducing the interleukin-25 (IL-25) secretion of tumor-associated fibroblasts." (PMID 33187226, 2020). "IL-25 influences both innate and adaptive immunity to induce type-2 inflammation; because a Th2 phenotype is generally associated with tolerance in the setting of tumors, it will be critical to define the functional significance of this important cytokine in the context of tumor immunity." (PMID 27165713, 2016). "Their pro-tumor activities can be curtailed by targeting cytokine signals (like IL-25) or reprogramming their inhibitory checkpoints (like PD-1), while their anti-tumor capacities can be harnessed by combining IL-33-based activation with checkpoint inhibitors." (PMID 40963622, 2025). "Adoptive transfer of IL-25-activated ILC2s into NSCLC-bearing mice results in increased tumor burden, metastasis, and reduced survival, confirming their pathogenic role." (PMID 40963622, 2025). "Adoptive transfer of IL‐25‐activated ILC2s in mice revealed increased tumour growth, metastasis and reduced survival through the accumulation of MDSCs in tumours." (PMID 40899118, 2025). "It has been demonstrated that Th2 cells, which are controlled by cytokines such as IL-25 and IL-33, stimulate tumorigenesis and metastasis, and that pharmacological inhibition successfully prevents tumor growth." (PMID 39996755, 2025). "IL-25 enhanced IL-13 production from tumor cells via STAT6 signaling pathways, resulting in the augmentation of a Th2-dominant microenvironment." (PMID 38607023, 2024). "In cases of tumor diseases, IL-25 has been found to suppress tumor growth in mice that have been transplanted with different tumor cell lines." (PMID 38879568, 2024). "Tumor‐bearing mice treated with IL‐25 showed a significant increase in serum IL‐5 levels and an increase in the number of eosinophils in the peripheral blood compared to the control group." (PMID 38775220, 2024). "Studies have showed that sustained innate IL-25 signaling helped to maintain the cancer permissive microenvironment of colorectal adenocarcinoma by preventing anti-tumor T cells and IFNγ-mediated immunity." (PMID 38818476, 2024). "Although numerous studies have shed light on the role of IL‐25 in tumor immunity, further investigations are needed, particularly in human tumors, to elucidate its precise effects." (PMID 38775220, 2024). "IL-25 production is stimulated by IL-4 and IL-13 cytokines—produced by tumor cells and Th2 cells—and periostin produced by dermal fibroblasts." (PMID 38607023, 2024). "Collectively, Th25 seems to be mostly involved in tumor progression through the secretion of IL-25, which leads to the promotion of type 2 immune responses." (PMID 37835465, 2023).
tumor (continued). "Since most studies on the mechanism of IL-25 in tumor development have been conducted in animal models and cell lines, the precise effect of IL-25 in human cancers requires further investigations." (PMID 37005677, 2023). "During tumor progression, IL-25 primarily promotes the proliferation and metastasis of tumor cells by activating various signaling pathways, including NF-κB and STAT3." (PMID 37005677, 2023). "Next, we sought to determine the TME composition after IL25-activated ILC2 transfer in CTX-lymphodepleted tumor-bearing mice." (PMID 37781372, 2023). "Next, in order to assess the effect of IL25-activated ILC2 cells on tumor growth, metastasis to the lung and overall survival, we transferred freshly sorted ILC2 cells or vehicle into lymphodepleted tumor-bearing mice twice per week for 4 weeks." (PMID 37781372, 2023). "In contrast, IL-25 was downregulated in malignant breast and prostate cancers, it was negatively correlated with cancer severity." (PMID 37005677, 2023). "The dysregulation of IL-25 is also correlated with the degree of tumor cell infiltration and the prognosis of cancer patients, providing a reference for further clinical studies." (PMID 37005677, 2023). "Since most studies on the mechanism of IL-25 in tumor development have been conducted in animal models and cell lines, the exact role of IL-25 in human cancer still needs to be supported by a large amount of clinical data." (PMID 37005677, 2023). "First, we wanted to assess the migration potential of IL25-activated ILC2 cells adoptively transferred i.v. into tumor-bearing mice." (PMID 37781372, 2023). "The specific function of IL-25 is also dependent on different tissues or organ-specific tumors or various stages of the disease, demonstrating both tumor-supportive and tumor-suppressive effects." (PMID 37005677, 2023). "In summary, our data supports a tumor-promoting role for the IL25/ILC2 axis both in humans and in mice." (PMID 37781372, 2023). "Consistent with the expression of Il13ra1 and Il17rb on tuft cells, IL25 or IL13 stimulation of tumor organoids increased their size, while treatment of organoids with an α-IL25 neutralizing antibody resulted in reduced organoid growth." (PMID 37898600, 2023). "Although the mechanisms of cancer pathogenesis are highly complex and the causes are difficult to predict, extensive research has shown that IL-25 appears to be a critical biomarker for tumor progression." (PMID 37005677, 2023). "IL-25 can also contribute to the malignant proliferation and differentiation of tumor cells by interfering with cell cycle and mediating interactions in various cells." (PMID 37005677, 2023). "Antibody-mediated neutralisation of IL-25 increased tumour burden in the AOM/DSS model of CAC and correlated with reduced eosinophils, although functional studies were not performed." (PMID 36263033, 2022). "While IL-25 levels were the best-identified predictor of RFS in this study, a combination of IL-25 levels and tumor diameter was better able to predict HBV-associated HCC patient OS." (PMID 36119529, 2022). "Mechanistically, IL-25 promoted intratumoral ILC2s, which sustained tumor-infiltrating MDSCs to suppress anti-tumor immunity." (PMID 35658010, 2022). "IL25 stimulated cancer organoid and cancer cells sphere formation and prevented the tumor from chemotherapy-induced apoptosis." (PMID 35359953, 2022). "CRC patients were stratified into IL25-high or IL25-low groups based on primary CRC tumor IL25 gene expression, and their prognosis was compared." (PMID 35658010, 2022). "IL-25 promotes tumorigenesis through activating ILC2s which sustain tumour M-MDSCs to suppress T cell and IFNγ-mediated anti-tumour immunity.IL-33 deficiency is associated with a reduction in tumour Tregs and mast cells." (PMID 36263033, 2022).
tumor (continued). "Here, we identified that CRC patients with high tumor IL25 expression have reduced survival, and that increased intratumoral ILC2s in CRC patient tissue are associated with impaired anti-tumor immunity." (PMID 35658010, 2022). "Further evidence showed that IL-25 promotes cell proliferation, inhibits apoptosis, and affects the development of fibrosis and hypoxic-ischemic injury, tumor metastasis and metabolism processes." (PMID 36298704, 2022). "Surprisingly, IL25 deletion significantly decreased tumor numbers and size in 16-week and the tumors of IL25KO mice were further attenuated by oxaliplatin, while there was only a decreased trend in tumors of WT mice whose diameters were smaller than 2 mm." (PMID 35359953, 2022). "Consistently, silencing or deletion of IL25 in vitro and in vivo, decreased the formation of tumor organoid and sphere formation, thus enhancing the sensitivity to oxaliplatin of tumor." (PMID 35359953, 2022). "IL-25 also has potent anti-tumor effects against several tumor types, including melanoma, through an increase in eosinophils recruitment into the tumor." (PMID 35432341, 2022). "As a member of the IL-17 cytokine subfamily, IL-25 plays a paradoxical role in cancer, both promoting and inhibiting tumor growth." (PMID 35885460, 2022). "Anti-tumour effect of IL-25 is B cell dependent as only observed in CD1 athymic nude mice but not in SCID mice." (PMID 36263033, 2022). "Genetic ablation of ILC2s or IL-25, or treatment with IL-25 blocking antibodies in these mice led to reduced tumor growth and increased survival." (PMID 36032129, 2022). "Mechanistically, ILC2-derived IL-4 and IL-13 in response to IL-25 signaling activated tumour M-MDSCs derived from Apc1322T/+ mice to express Arginase 1 (Arg1) and suppress CD8+ T cells." (PMID 36263033, 2022). "In other models, IL-25 itself exhibits anti-tumor activity through the induction of apoptosis in cancer cells without affecting nonmalignant cells." (PMID 35432341, 2022). "The AUC value for IL-25 was higher than that for all other predictors with the exception of tumor number (p < 0.05), and in an analysis of multivariate for predictors associated with patient RFS, the HR for IL-25 was the greatest." (PMID 36119529, 2022). "The RFS nomogram C-index value (0.645) was higher than that for HBV DNA (0.542), AFP (0.564), tumor count (0.538), encapsulation of tumor (0.561), IL-25 (0.549), tumor diameter (0.582), and microvascular invasion (0.559) (all p < 0.001)." (PMID 36119529, 2022). "On the one hand, IL-25 has been shown to increase the number of B cells and eosinophils in the tumor microenvironment, which is thought to be a tumor-suppressive function." (PMID 35054524, 2022). "Based on our findings, injection of IL25 neutralizing antibody would reduce the tumor in AOM/DSS treated mice." (PMID 35359953, 2022). "Genetic deletion of IL25 inhibited tumor formation and growth and prolonged survival in AOM/DSS-treated mice." (PMID 35359953, 2022). "Tumor recurrence differed significantly between cases with low and high levels of serum IL-25 determined via a multivariate analysis approach, with elevated preoperative IL-25 levels being independent predictors of decreased OS and RFS in these cases." (PMID 36119529, 2022). "Impressively, compared with control and adjacent colon specimens (IHC-Score = 1.33 and 1.50), the expression of IL25 had a rising trend in WT 10-week tumor (IHC-Score = 2.6) and was remarkably elevated in WT 16-week tumor (IHC-Score = 6.5)." (PMID 35359953, 2022). "The tumor‐supportive roles of IL‐25, which in this regard is mainly produced by CAFs, have been shown to promote cell cycle, induce EMT and metastasis." (PMID 34128588, 2021). "The tumor‐suppressive role of IL‐25 is mainly attributed to the infiltration of eosinophils and B cells into the tumor microenvironment and induction of apoptosis." (PMID 34128588, 2021).
tumor (continued). "Although a couple of mechanisms related to IL‐25 involvement in tumor development have been discovered, it is necessary to be investigated more detailed underlying mechanisms." (PMID 34128588, 2021). "Upon IL‐25 ligation to highly IL‐25R‐expressing tumor cell lines, DD‐containing proteins, including TRADD and FADD, are recruited to the receptor complex." (PMID 34128588, 2021). "In contrast, IL‐25 ligation to IL‐25R on tumor cells mediates antitumor effects through induction of apoptosis and infiltration of eosinophils and B cells." (PMID 34128588, 2021). "As has been discussed, although IL‐25 inhibits tumor growth in some cases, it has been shown that IL‐25 also plays a pivotal role in cancer progression in several studies." (PMID 34128588, 2021). "It has been confirmed that IL‐25 exerts a tumor‐suppressive role through inducing infiltration of eosinophils and B cells into the tumor microenvironment and activating the apoptotic pathways." (PMID 34128588, 2021). "In cancers in which IL‐25 has a tumor‐suppressive function, employing IL‐25‐enhancing approaches, such as Virulizin® and dihydrobenzofuran administration, has potentially inhibited tumor cell growth." (PMID 34128588, 2021). "IL‐25, as a member of the IL‐17 cytokine subfamily, exerts a paradoxical role in cancer, including tumor supportive and tumor suppressive." (PMID 34128588, 2021). "Non‐CSCs secrete IL‐25 into the tumor microenvironment, and secreted IL‐25 interacts with IL‐17RB on CSCs." (PMID 34128588, 2021). "Several primary tumors and tumor cell lines have been described to produce alarmins as IL-25 and TSLP." (PMID 33233582, 2020). "We found that the tumor formation rate in the group with IL-25-induced M2 macrophages was higher than that in the group with M0 macrophage (8/8 vs. 5/8, p = 0.06)." (PMID 31296243, 2019). "In our study, the intensity of IL-25 immunofluorescent staining of HCC tumor tissue was positively correlated with the intensity of CD206 staining (M2 marker)." (PMID 31296243, 2019). "After a 2‐week treatment, the tumor sizes of cisplatin (5 mg/kg) alone treated nude mice (n = 8) were smaller than that in cisplatin along with IL‐25 (5 ng/mL) treated nude mice." (PMID 31044552, 2019). "The average reduced rates of tumor volume were significantly lower in IL‐25 and cisplatin treated group than that in cisplatin treated control group." (PMID 31044552, 2019). "Consistent with our findings in human breast tissues, the immunohistochemical analysis also revealed that tumor-infiltrating cells in MMTV-PyMT mice expressed high levels of IL-25." (PMID 27909985, 2017). "Most F4/80+ or CD4+ cells were co-stained with anti-IL-25, suggesting that these cells are the major source of IL-25 in the tumor." (PMID 27909985, 2017). "By using a tumor resection model, we demonstrated that the in vivo treatment of Q2-3 efficiently induced the TAFs to secrete IL-25 at high levels." (PMID 28674499, 2017). "Since anti-IL-25 treatment resulted in a reduction of IL-4-producing Th2 cells, we then examined the polarization of tumor macrophages in the MMTV-PyMT tumor model." (PMID 27909985, 2017). "For further confirmation, CD4+ T cells and CD11b+F4/80+Gr-1- macrophages were purified from tumor tissues, and analyzed for the mRNA expression of IL-25." (PMID 27909985, 2017). "We found that IL-25 promoted tumor metastasis to the lung, possibly via regulating type 2 immune responses in the tumor microenvironments." (PMID 27909985, 2017). "Some tumor-associated stromal cells can produce tumor suppressor factors, such as nucleoside NME1, Kangai 1 (KAI1/CD82) and IL-25, in the tumor microenvironment, and these activities can restrict the development or metastasis of surrounding tumor cells." (PMID 28674499, 2017). "The mRNA analysis showed a significant increase of IL-25 expression in the tumor tissues compared with normal mammary tissues." (PMID 27909985, 2017).